PCDHAC1 (protocadherin alpha subfamily C, 1)
Description:
Potential calcium-dependent cell-adhesion protein. May be involved in the establishment and maintenance of specific neuronal connections in the brain.
Synonyms: PCDH-alpha-C1
Tractability: Antibody: its Gene Ontology location is reachable by antibodies, with high confidence; UniProt places it where antibodies can reach, with medium confidence; UniProt predicts a signal peptide or a membrane-spanning region.
Gene: Protein-coding gene on chromosome 5 (140,926,299 to 141,012,347, forward strand). Ensembl gene ENSG00000248383.
Subcellular location: Cell membrane
Subcellular location (Human Protein Atlas): Nucleoli; Nucleoplasm; Vesicles
Gene Ontology:
Molecular function: cell adhesion molecule binding; calcium ion binding
Biological process: cell adhesion; nervous system development; homophilic cell-cell adhesion
Cellular component: plasma membrane; membrane
Genetic constraint (gnomAD): Loss-of-function variants: 42 observed, 62.51 expected, observed/expected ratio (o/e) 0.67, 90% interval 0.52 to 0.87. The upper end of that interval is the gene's LOEUF score, 0.87, which puts it in group 3 of 6, group 1 being the genes least tolerant of losing a copy. Missense variants: 1,160 observed, 1,289.8 expected, observed/expected ratio (o/e) 0.9, 90% interval 0.86 to 0.94. Synonymous variants: 468 observed, 525.72 expected, observed/expected ratio (o/e) 0.89, 90% interval 0.82 to 0.96.
Homologues: Orthologues: guinea pig PCDHAC1 (87% identical), mouse Pcdhac1 (84% identical). Paralogues in human: PCDHAC2 (50% identical), PCDHA7 (43% identical), PCDHA9 (42% identical), PCDHA13 (42% identical), PCDHA4 (42% identical), PCDHA8 (42% identical), PCDHA5 (42% identical), PCDHA10 (42% identical), PCDHA3 (42% identical), PCDHA6 (42% identical), PCDHA12 (41% identical), PCDHA1 (41% identical), and 49 more.
Diseases named in the same sentence as PCDHAC1 in open-access papers:
PCDHAC1 is named in the same sentence as 2 diseases in open-access papers, as found by Europe PMC text mining. Sharing a sentence is not in itself a finding about the gene and the disease.
PCDHAC1 shares sentences with these, for which no sentence is quoted: kidney tumor (1 paper); schizophrenia (1).